HLA-DRB1 (major histocompatibility complex, class II, DR beta 1)
Diseases named in the same sentence as HLA-DRB1 in open-access papers (continued):
Sharing a sentence is not in itself a finding about the gene and the disease.
leishmaniasis (3 papers, 2016 to 2021). Infectious disease that is transmitted through the bite of hematophagous female phlebotomine sand flies. "The finding that protection-associated HLA-DRB1 alleles are consistently associated with leishmaniasis, and share common binding motifs, highlights that epitopes that bind to these HLA alleles are the most likely to confer a disease-specific immune response." (PMID 33803005, 2021). "One study does point toward common amino acid polymorphisms and epitope binding repertoires in HLA-DRB1 associated with lower Leishmaniasis susceptibility." (PMID 34696166, 2021). "To explore the mechanisms underpinning the HLA associations in leishmaniasis, we identified several amino acid variants that were shared entirely across either the risk- or the protection-associated HLA-DRB1 alleles included in this study." (PMID 33803005, 2021). "In contrast, HLA-DRB1 alleles are widely associated with leishmaniasis." (PMID 33803005, 2021). "Nonetheless, the association of HLA-DRB1 with leishmaniasis susceptibility was robust." (PMID 33803005, 2021). "The data presented in this study strongly suggest that polymorphism in the HLA-DRB1 region, and the resulting variation in the epitope binding pocket, mediates the association between HLA-DRB1 and leishmaniasis disease outcome." (PMID 33803005, 2021). "We argue that the limitations of HLA typing methods across the included studies do not invalidate the robust association of the HLA-DRB1 locus with leishmaniasis, their inclusion in our study and the subsequent results of our work." (PMID 33803005, 2021). "Other variants of the HLA-DRB1 locus were not consistently associated with (lower or higher) susceptibility to leishmaniasis." (PMID 33803005, 2021). "Thus, the amino acid sequences of the different leishmaniasis-associated HLA-DRB1 alleles were aligned to identify distinct substitutions in the HLA profile that explain the disease association status." (PMID 33803005, 2021). "It does mean that there might be other, yet unknown, leishmaniasis-associated HLA alleles that we could not include in our analysis, HLA-DRB1 or otherwise, which could have led to additional insights." (PMID 33803005, 2021).
non-Hodgkin lymphoma (3 papers, 2011 to 2024). Distinct from Hodgkin lymphoma both morphologically and biologically, non-Hodgkin lymphoma (NHL) is characterized by the absence of Reed-Sternberg cells, can occur at any age, and usually presents as a localized or generalized lymphadenopathy associated with fever and weight loss. "We previously identified associations with non-Hodgkin lymphoma (NHL) and the HLA-DRB1*01:01 allele and extended ancestral haplotype (AH) 8.1 (HLA-A*01-B*08-DR*03-TNF-308A)." (PMID 22096508, 2011).
Onset (3 papers, 2020 to 2023). The age group in which disease manifestations appear. "Our objective was to investigate the risk/resistance influence of HLA-DPB1 alleles in Hellenic patients with early- and adult-onset MS (EOMS/AOMS), and possible associations with the HLA-DRB1*15:01 risk allele." (PMID 32560041, 2020).
prostate carcinoma (3 papers, 2012 to 2025). A carcinoma that arises from epithelial cells of the prostate gland. "A total of 20 genes are involved in these intra-category multimorbid relationships and are mainly related to the human leukocyte antigen (HLA) complex (such as HLA-DQA1 and HLA-DRB1), histone clusters (such as HIST1H1B and HIST1H2AJ), and tumors (such as TERT and NOTCH4 for prostate cancer)." (PMID 34225788, 2021).
relapsing-remitting MS (3 papers, 2022 to 2024). "By integrating genetic markers such as HLA-DRB1*15:01 into the McDonald Criteria, one would be able to differentiate between subtypes such as relapsing-remitting MS and primary-progressive MS." (PMID 39684620, 2024).
SARS-CoV infection (3 papers, 2008 to 2022). "For example, Ng reported that SARS-CoV infection was associated with HLA-B*0703 and HLA-DRB1*0301 in HongKong population, however, Lin's results showed that HLA-B*4601 and HLA-B*5401 were closely related to SARS-CoV infection." (PMID 18312678, 2008).
scleroderma (3 papers, 2012 to 2018). Scleroderma is a rare autoimmune connective tissue disorder characterized by abnormal hardening of the skin and, sometimes, other organs. "A strong relationship between HLA haplotypes and specific scleroderma-related autoantibodies is also confirmed, with ACA being associated with HLA class II genes, namely HLA-DQB1 and HLA-DRB1." (PMID 31431952, 2018).
thymoma (3 papers, 2008 to 2013). A neoplasm arising from the epithelial cells of the thymus. "Specific changes related to MG-thymoma included HLA-DRB1, associated with a haplotype predictive of MG susceptibility in female with specific gene variants." (PMID 18545673, 2008). "Its expression is significantly higher in thymus compared to colon, with a putative 5′ end-modified HLA-DRB1-002 transcript in MG-thymoma." (PMID 18545673, 2008). "Nevertheless, HLA-DRB1*13:01 was weakly negative associated with both EOMG and LOMG separately, but was highly significant when the total MG population (excluding MG with thymoma) was investigated." (PMID 22590574, 2012). "To test whether the suggested negative association of HLA-DRB1*13:01 found in both EOMG and LOMG could be a general protective factor for MG, we pooled all MG subgroups (except MG with thymoma) and compared the groups with controls." (PMID 22590574, 2012).
typhoid fever (3 papers, 2017 to 2021). A bacterial infectious disorder contracted by consumption of food or drink contaminated with Salmonella typhi. "The application of imputation-based fine-mapping across the extended HLA region provided a confident datum to show that HLA-DRB1*04:05 allele as a protective factor against typhoid fever with its genotyped single nucleotide polymorphism (SNP), rs7765379." (PMID 33562108, 2021). "In addition, HLA-DRB1*12 and *12:02 had also been associated with protection from periodontal oral infections and recurrent typhoid fever." (PMID 32776973, 2020). "However, the alleles of HLA-DRB1*0301/6/8, HLA-DQB1*0201-3 and TNFA*2 (−308) have been reported to be associated with increased susceptibility to typhoid fever." (PMID 33562108, 2021).
VKH disease (3 papers, 2009 to 2019). "The aim of this study was to investigate the relationship between visual prognosis and HLA-DRB1*04 alleles during systemic corticosteroid therapy in patients with VKH disease." (PMID 31699055, 2019). "In conclusion, although highly significant, the immunogenetic basis of HLA-DRB1 associations with susceptibility to VKH syndrome seems to be weaker in south Indian Tamils than in Japanese or Hispanic patients." (PMID 20216938, 2010). "The HLA-DRB1 association with susceptibility to VKH syndrome seems weaker in Indian patients compared to Japanese or Hispanic patients, suggesting a different non-HLA immunogenetic background in Indian VKH patients." (PMID 20216938, 2010). "Association of the HLA-DRB1 *0405 allele and VKH disease has already been reported in the other races." (PMID 19756183, 2009). "Out of the HLA-DRB1 *04 subtypes, HLA-DRB1 *0405 had the strongest association with the VKH disease." (PMID 19756183, 2009). "We report that alleles of HLA-DRB1*04 might affect visual prognosis and be related to early response after initiation of treatment in VKH disease." (PMID 31699055, 2019). "We can guess that Alleles of HLA-DRB1*04 might affect visual prognosis and be related to early response after initiation of treatment in VKH disease." (PMID 31699055, 2019). "Alleles of HLA-DRB1*04 might affect visual prognosis and be related to early response after initiation of treatment in VKH disease." (PMID 31699055, 2019). "Kim and associates found that HLA-DRB1 *0405 was greatly increased in patients with VKH syndrome among Koreans and might have an important role in the development of the clinical course of VKH." (PMID 19756183, 2009). "To conclude, patients with VKH had a higher incidence of HLA-DRB1 *0405, indicating that the HLA-DRB1 *0405 allele might play a role in the pathogenesis of VKH disease." (PMID 19756183, 2009). "Consequently, this finding suggests that HLA-DRB1 *0405 allele might play a role in the pathogenesis of VKH disease." (PMID 19756183, 2009). "HLA-DRB1 frequencies (generic DR types) in patients with VKH syndrome compared to patients with SO and to healthy controls." (PMID 20216938, 2010). "Alternatively, if the weak association of VKH disease with HLA-DRB1*0101 and HLA-DRB1*0403/HLA-DRB1*0407 is considered as relevant, the susceptibility epitope shared by the five alleles would be LLEQRRA in the third hypervariable region of DRβ1 molecules." (PMID 20216938, 2010). "In a cohort of 57 Japanese patients, the association of HLA-DRB1*0405/HLA-DRB1*0410 was stronger with prolonged than nonprolonged VKH disease." (PMID 20216938, 2010). "We performed complete HLA-DRB1 genotyping and found that HLA-DRB1 *0405 was significantly associated with VKH disease, and no such association was noted with HLA-DRB1 *0404." (PMID 19756183, 2009).
abdominal aortic aneurysm (2 papers, 2012 to 2019). Enlargement and ballooning of the vessel that supplies arterial blood to the abdomen, pelvis and legs. "Interestingly, HLA-DRB1 polymorphisms are linked to chronic periaortitis patients (with incidence of aneurysm development) and abdominal aortic aneurysm patients, suggesting these genes have significance in aortic aneurysm formation." (PMID 22479353, 2012).
Acute hepatitis (2 papers, 2023 to 2025). Acute hepatic injury resulting from inflammation typically accompanied by increased serum alanine transaminase activity. "In this study, we hypothesized that HLA-DRB1 04:01 in the host may also be a potential predisposing factor of acute hepatitis caused by other viruses." (PMID 40079016, 2025). "HLA-DRB1 04:01 may predispose children to acute hepatitis from various viruses, including AV2, AAV2, and possibly respiratory viruses, which requires clinical attention." (PMID 40079016, 2025). "From the present case, we inferred that the HLA-DRB1 04:01 genotype may be a factor that predisposes to acute hepatitis caused by AV2." (PMID 40079016, 2025). "Based on this proposed mechanism, we assumed that host HLA-DRB1 04:01 was a possible predisposing factor for acute hepatitis caused by various viruses, including AV2, AAV2, and possibly respiratory viruses, although the causal relationship could not be confirmed." (PMID 40079016, 2025). "HLA-DRB1*15, described in some AIH non-Caucasian patients, was present in case 7 (acute hepatitis without AIH)." (PMID 37893221, 2023).
Addison’s disease (2 papers, 2020 to 2024). "Two alleles (HLA-DRB1*03:01 and DRB1*04:04) that we found in greater proportions in our study have been conferred with an increased risk of Addison’s disease." (PMID 31963191, 2020).
allergic bronchopulmonary aspergillosis (2 papers, 2025). Allergic bronchopulmonary aspergillosis (ABPA) is a rare immunologic pulmonary disorder caused by hypersensitivity to Aspergillus fumigatus, clinically manifesting with poorly controlled asthma and recurrent pulmonary infiltrates. "The HLA-DRB1*15:01 allele, a major genetic risk factor of MS, is also associated with susceptibility to allergic bronchopulmonary aspergillosis (ABPA)." (PMID 40528008, 2025).
alopecia areata (2 papers, 2010 to 2022). Loss of scalp and body hair involving microscopically inflammatory patchy areas. "Several genes encoding HLA (human leukocyte antigen) variants have been correlated with alopecia areata, among them, polymorphisms in HLA-DRB1 are a major contributor to the disease phenotype." (PMID 36292745, 2022). "A recent meta-analysis has shown that HLA-DRB1*04 and HLA-DRB1*16 variants increase the risk of alopecia areata, while HLA-DRB1*0301, HLA-DRB1*09 and HLA-DRB1*13 variants are protective." (PMID 36292745, 2022).
amebiasis (2 papers, 2018 to 2023). A parasitic infectious disorder caused by amoebas. "Furthermore, as reported, MHC polymorphisms such as HLA-DRB1*03:0101 and HLA-DRB1*11:0101 in humans may be associated with higher susceptibility to amebiasis." (PMID 37637465, 2023). "HLA-DRB1*03:0101 and HLA-DRB1*110,101 may have a role in susceptibility to amebiasis." (PMID 30416723, 2018).
ANCA-associated vasculitis (2 papers, 2017 to 2024). "Meanwhile, HLA-DRB1*09:01 has been shown to be associated with antineutrophil cytoplasmic antibody-associated vasculitis in Japan." (PMID 39744136, 2024).
aplastic anemia (2 papers, 2016 to 2022). Anemia resulting from bone marrow failure (aplastic or hypoplastic bone marrow). "A 6-year-old girl with idiopathic severe aplastic anemia underwent unrelated BMT from a 4/6 HLA-matched (mismatches in HLA-A and HLA-DRB1 loci) male donor after 2 courses of immunosuppressive therapy consisting of rabbit ATG and cyclosporin A in combination with eltrombopag." (PMID 35356922, 2022).
autoimmune type 1 diabetes (2 papers, 2013 to 2025). Autoimmune disease wherein the body's own immune system attacks and destroys the cells within the pancreas that produce insulin. "A robust link has been found between early-onset OCD and HLA-class II, particularly with the allele HLA-DRB1-04, involved in autoimmune type-1 diabetes." (PMID 40869088, 2025).
berylliosis (2 papers, 2005 to 2019). "Previous studies have identified the HLA-DRB1 alleles belonging to the *01 group as negatively associated with berylliosis, while the HLA-DRB1 variants Ser11, Tyr26, Asn37, Glu71 and Arg74 and the HLA-DQ variant Gly86 were positively associated with BH." (PMID 16098233, 2005).
childhood asthma (2 papers, 2020 to 2022). "For example, highly polymorphic HLA class II genes, such as HLA-DQA1 and HLA-DRB1, are implicated in childhood asthma susceptibility and serum immunoglobulin E (IgE) production." (PMID 36118895, 2022).
chronic hepatitis B (2 papers, 2012 to 2024). "Comparable results were observed in Iranian patients, where HLA-DRB1*15:01 was typically associated with protection against chronic hepatitis B infection, as reported by Baniaghil." (PMID 38392185, 2024). "In the chronic hepatitis B group, the HLA-DRB1*06:03:01 allele frequency was significantly lower compared to the normal control group, indicating a substantial correlation (OR = 0.19; 95% CI = 0.08–0.38, p = 0.002)." (PMID 38392185, 2024).
chronic myeloid leukemia (2 papers, 2020 to 2024). "Clone 100 has been isolated from bone marrow of patient 3,087, 5 weeks after donor lymphocyte infusion (DLI) for relapsed chronic myeloid leukemia (CML) after alloSCT and was restricted to HLA-DRB1*03:01." (PMID 32218783, 2020).
Coronary arteriosclerosis (2 papers, 2024). "Coronary arteriosclerosis shared 10 GWS genes with AD (BAG6, C6orf10, HLA-DQB1, HLA-DRA, HLA-DRB1, NDUFAF6, NME7, PLCG2, PRRC2A, and TRIB1), while myocardial infarction shared three genes with AD (HLA-DRA, PHB, and RP11-81K2.1)." (PMID 39201500, 2024).
cryptorchidism (2 papers, 2011 to 2022). The failure of one or both testes of a male fetus to descend from the abdomen into the scrotum during the late part of pregnancy. "Sixty prepubertal boys with cryptorchidism and sixty healthy boys were examined for anti-sperm antibodies by indirect immunobead test as well as for their HLA-DRB1 and -DQB1 alleles using DNA obtained from peripheral blood leukocytes." (PMID 21955839, 2011). "HLA-DRB1*11 was also, albeit weakly, associated with bilateral cryptorchidism." (PMID 21955839, 2011). "On the other hand, we obtained an unexpected finding of a strong difference between familial (but not sporadic) cryptorchidism (and/or with history of infertility within these families) and healthy controls, showing a high risk for HLA-DRB1*11 bearers." (PMID 21955839, 2011). "Furthermore, there is evidence that cryptorchidism may facilitate the emergence of antisperm antibodies and thus the development of autoimmunoinfertility, as we address here for SAA1 and HLA-DRB1." (PMID 36613967, 2022).
cutaneous leishmaniasis (2 papers, 2013 to 2016). Leishmaniasis affecting the skin. "We studied the association of variations at HLA class I (HLA-A, HLA-B) and HLA class II (HLA-DRB1, HLA-DQB1) loci with susceptibility to localised cutaneous leishmaniasis in Sinhalese in Sri Lanka." (PMID 27301744, 2016). "Allele frequency of HLA-DRB1*13 (P = 0.0228, Pc = 0.3317) was conspicuous only in the non-recurrent cutaneous leishmaniasis groups, whereas HLA-B*49 was prominent in the recurrent disease group." (PMID 23638805, 2013).
dementia (2 papers, 2020 to 2022). Loss of intellectual abilities interfering with an individual's social and occupational functions. "Also, we aimed to investigate the association of candidate loci with the age at the onset of AD and confirmed that the candidate genes including HLA-DRB1, CD2AP, and PTK2B may contribute to the development of early onset dementia." (PMID 32116649, 2020).
EBV infection (2 papers, 2015 to 2024). "HLA-DRB1*1501 was associated with a 3-fold elevation in MS risk, and EBV infection was associated with a 2.6-fold elevation in MS risk." (PMID 26656273, 2015). "However, EBV infection alone was significantly associated with MS (OR, 2.60; 95%CI, 1.48–4.59), and HLA-DRB1*1501 significantly increased the risk of MS (OR, 3.06; 95%CI, 2.30–4.08)." (PMID 26656273, 2015). "Furthermore, our data indicate that the combined effects of HLA-DRB1*1501 positivity and Epstein-Barr virus infection result in an up to six-fold increased risk of MS." (PMID 26656273, 2015). "The additive (S) and multiplicative interaction indexes (OR) between EBV infection and HLA-DRB1*1501 and their 95% confidence intervals (95%CI) were calculated for each study and then combined in a meta-analysis." (PMID 26656273, 2015). "There was significant interaction between HLA-DRB1*1501 positivity and EBV infection based on the additive scale (S = 1.43, 95%CI = 1.05–1.95, P = 0.023; AP = 0.29, 95%CI, 0.12–0.47, P = 0.001; RERI = 1.44, 95%CI, 0.30–2.58, P = 0.013)." (PMID 26656273, 2015). "We therefore conducted a meta-analysis on the effect of the interaction between HLA-DRB1*1501 and EBV infection on MS." (PMID 26656273, 2015). "To better illuminate the independent and combined effects of EBV infection and HLA-DRB1*1501 in the etiology of MS, we conducted a meta-analysis to evaluate the interaction between these two factors in MS risk." (PMID 26656273, 2015). "Due to hereditary nature of the HLA-DRB1*1501 genotype, effective intervention and prevention measures can be implemented by monitoring EBV infection status." (PMID 26656273, 2015). "We identified a significant additive interaction between EBV infection and HLA-DRB1*1501 in the risk of MS; however, we did not observe an interaction based on the multiplicative scale." (PMID 26656273, 2015). "In conclusion, our meta-analysis identified an interaction between HLA-DRB1*1501 and EBV infection for the risk of MS on an additive scale; however, we did not observe a significant interaction between these factors on a multiplicative scale." (PMID 26656273, 2015). "Consequently, we suggest that EBV infection should be prevented in healthy individuals (particularly HLA-DRB1*1501 carriers)." (PMID 26656273, 2015). "EBV infection and HLA-DRB1*1501-positivity were dichotomized." (PMID 26656273, 2015). "Moreover, data from individual studies on the interaction between HLA-DRB1*1501 and EBV infection are not entirely consistent." (PMID 26656273, 2015).
endometrial cancer (2 papers, 2020 to 2021). Primary or metastatic malignant neoplasm involving the endometrium (mucous membrane that lines the endometrial cavity). "Our results identified CD74, HLA-DRB5, CD52, HLA-DPB1 and HLA-DRB1 as possible valuable genetic markers for the diagnosis and prognosis of endometrial cancer and provided a theoretical basis for immunotherapy targets for its clinical treatment." (PMID 33159014, 2020).